S100A8 (S100 calcium binding protein A8)
Diseases named in the same sentence as S100A8 in open-access papers (continued):
Sharing a sentence is not in itself a finding about the gene and the disease.
invasive carcinoma (continued). "PD-L1 + IC was more frequently observed in S100A8+ IC (+) group compared to S100A8+ IC (−) group in both pre-invasive and invasive carcinomas (p = 0.006, p < 0.001, respectively)." (PMID 33146829, 2021). "S100A8 was expressed in both TCs and ICs of pre-invasive and invasive carcinomas." (PMID 33146829, 2021). "In invasive carcinoma, infiltration of S100A8+ IC showed a weak positive correlation with infiltration of CD4+ TIL (rho = 0.263) and a moderate positive correlation with infiltration of CD8+ and FOXP3+ TIL and PD-L1+ IC (rho = 0.474, 0.482 and 0.525, respectively)." (PMID 33146829, 2021). "As MDSCs are known to be associated with regulatory T cell infiltration and PD-L1 induction, we analyzed the correlation between S100A8+ IC, TIL subsets, and PD-L1+ IC infiltration in pre-invasive and invasive carcinomas." (PMID 33146829, 2021). "Furthermore, in combined analyses of S100A8+ IC and other IC subset infiltration, we found that infiltration of S100A8+ IC was associated with decreased disease-specific survival in the PD-L1+ IC (−), CD8+ TIL-low, and FOXP3+ TIL-low subgroups in invasive carcinomas." (PMID 33146829, 2021). "S100A8+ ICs, but not S100A8+ TCs, were significantly higher in number in invasive carcinoma than in pre-invasive carcinoma." (PMID 33146829, 2021). "In our study, in terms of frequency of positive cases, S100A8+ TCs was found in 30.7% (54/176) of pre-invasive carcinomas and 33.4% (175/524) of invasive carcinomas without a statistical difference (data not shown)." (PMID 33146829, 2021). "However, as the number of HR-negative pre-invasive carcinoma was quite small (n = 21), and HR-positive tumors generally showed no S100A8+ IC infiltration, further large-series studies are warranted to confirm this finding." (PMID 33146829, 2021). "Additionally, we found that the difference in S100A8+ IC infiltration between pre-invasive and invasive carcinomas was evident in HR-negative tumors, but not in HR-positive tumors." (PMID 33146829, 2021). "However, S100A8, LAG3, CXCL10, CXCL9 and BIRC5 showed a difference in fold change between DCIS and invasive carcinoma although statistically not significant (adjusted p value > 0.05)." (PMID 34504204, 2021).
keloid (2 papers, 2018 to 2024). An irregularly shaped, elevated mark on the skin caused by deposits of excessive amounts of collagen during wound healing. "S100A7 and S100A8 exhibited the second and third greatest upregulation in keloids, respectively." (PMID 38622256, 2024). "Of those, six genes (i.e., OPCML, S100A7, S100 calcium binding protein A8 [S100A8], KANK4, PTPRD, tenascin XB [TNXB]) were significantly differentially expressed between keloid and immature scar samples." (PMID 38622256, 2024).
latent infection (2 papers, 2019 to 2021). "Our results suggest a potential mechanism by which HCMV latent infection downregulates S100A8/A9: repressive CTCF binding to the enhancer region of the S100A8/A9 genomic locus is increased during HCMV latency, likely mediated by the viral gene product US28." (PMID 34042564, 2021). "Together, these results show that S100A8/A9 is downregulated during latent infection with HCMV both intra- and extracellularly." (PMID 30677738, 2019). "This showed that latent infection downregulates the neutrophil chemoattractants S100A8/A9, thus suppressing neutrophil recruitment to latently infected cells." (PMID 30677738, 2019). "The ability of HCMV to target S100A8/A9 during latent infection may have additional roles beside evasion of neutrophil targeting." (PMID 30677738, 2019). "We show that latent infection drives increased CTCF occupancy on the enhancer region of these genes, and that US28 expressed in isolation in myeloid cells is able to drive decreased S100A8 and S100A9 secretion." (PMID 34042564, 2021).
myeloid neoplasm (2 papers, 2023 to 2024). Proliferation of myeloid cells originating from a primitive stem cell. "While there is ample evidence showing that S100A8 possesses tumorigenic potentials in many solid tumors, it has also been associated with an increased risk of hematological malignancies, especially myeloid neoplasms." (PMID 37240094, 2023). "The alarmin heterocomplex S100A8/A9 secreted by the BM has been reported as a candidate driver initiating the inflammatory crosstalk in myeloid neoplasm and MF." (PMID 39157630, 2024). "Collectively, through actions on immune response, oxidative stress, and cell growth, S100A8 helps shape the microenvironment that favors the clonal expansion of the myeloid neoplasms." (PMID 37240094, 2023).
nasal polyps (2 papers, 2010 to 2022). "Decreased expression of S100A8 and S100A9, members of the epidermal differentiation complex at chromosome 1q21, in epithelial cells from CRS patients with and without nasal polyps was recently reported." (PMID 20625511, 2010).
nasopharyngeal carcinoma (2 papers, 2023). A carcinoma arising from the nasopharyngeal epithelium. "S100A8/A9 overexpression notably improves the viability of nasopharyngeal carcinoma cells, and S100A8/A9 knockdown represses proliferation and colony formation by inhibiting the PI3K/Akt pathway." (PMID 37701037, 2023).
pancreatic ductal adenocarcinoma (2 papers, 2018 to 2025). An infiltrating adenocarcinoma that arises from the epithelial cells of the pancreas. "Pancreatic ductal adenocarcinoma (PDAC) is characterised by a highly reactive microenvironment, harbouring a variety of cell types, including S100A8/S100A9-expressing monocytes." (PMID 30558665, 2018).
plaque psoriasis (2 papers, 2016 to 2019). "For immunohistochemistry of calprotectin, a skin specimen from a patient with psoriasis vulgaris was used as a positive control, because S100A8 and S100A9 are up-regulated in psoriatic epidermis." (PMID 27442430, 2016).
Pneumocystis infection (2 papers, 2010 to 2022). "Other DAMPs identified in the proteomics included protein S100-A8 and protein S100-A9, which were slightly increased in B cell exosomes after Pneumocystis infection, although not significantly." (PMID 35465354, 2022).
pneumonitis (2 papers, 2023 to 2024). An inflammatory process affecting the lung parenchyma. "The serum S100A8/A9 levels in patients with CAP was 1.59 ± 1.32 ng/mL, which was approximately five and two times higher than those in healthy controls and those in children with pneumonitis, respectively." (PMID 37180431, 2023). "In this study, serum S100A8/A9 levels in children infected with CAP (1.59 ± 1.32 ng/mL) were five times higher than those in healthy children (0.31 ± 0.21 ng/mL) and approximately two times higher than those in children with pneumonitis (0.79 ± 0.40 ng/mL)." (PMID 37180431, 2023). "Similarly, H&E-stained lung sections of IAV-infected S100a8-Cre/Acvr1bfl/fl animals revealed a moderate degree of tissue injury with a more prominent pneumonitis compared to controls, which did not involve the extreme honeycomb appearance of S100a8-Cre/Inhbafl/fl lungs." (PMID 38476229, 2024).
sarcopenia (2 papers, 2021). Progressive decline in muscle mass due to aging which results in decreased functional capacity of muscles. "Their MS analysis revealed that the sarcopenia group showed 2-fold higher cathepsin D levels and 4.2-fold higher S100A8 levels than the control group." (PMID 34943268, 2021). "Moreover, Western blot tests showed that sarcopenia patients had an enhanced detection of S100A8." (PMID 34943268, 2021).
spondylarthropathy (2 papers, 2006 to 2025). "Analysis of key common proteins has revealed that the proteins with the highest expression in the spondyloarthritis group are S100A8 and S100A9." (PMID 39877611, 2025). "Out of the eight co-expressed highly expressed proteins, S100A8, S100A9, SERPING1, CECR1, and FERMT3 are all associated with inflammation, with S100A8 and S100A9 being clinically confirmed to be closely related to spondyloarthritis." (PMID 39877611, 2025). "This further confirms the close relationship of S100A8 and S100A9 with the phenotype of this spondyloarthritis." (PMID 39877611, 2025). "It is evident that the high expression of S100A8, S100A9, SERPING1, ZYZ, VCL, and FERMT3 is positively correlated with spondyloarthritis." (PMID 39877611, 2025). "S100A8 and S100A9 may be markers of spontaneous spondyloarthritis in crab-eating macaques." (PMID 39877611, 2025). "It is hypothesized that S100A8 and S100A9 could serve as potential predictive biomarkers for spondyloarthritis in non-human primates." (PMID 39877611, 2025). "It is hypothesized that S100A8 and S100A9 could serve as potential predictive biomarkers for this spondyloarthritis in non-human primates." (PMID 39877611, 2025).
streptococcal pneumonia (2 papers, 2013 to 2017). A febrile disease caused by streptococcus pneumoniae. "In line, in a mouse model of streptococcal pneumonia anti-S100A8 and anti-S100A9 caused neutrophil and macrophage recruitment to alveoli to diminish by 70–80%." (PMID 23874727, 2013). "Blockade of S100a8 and S100a9 also suppresses neutrophil migration in response to lipopolysaccharide in the air pouch and monocyte/macrophage infiltration during streptococcal pneumonia." (PMID 29326691, 2017).
T cell lymphoma (2 papers, 2019 to 2022). "The hypoxia status is positively related to the expression of S100A8/A9 which can induce the downregulation of tumor growth and PD-L1 expression through ERK1/2 signaling in NK/T-cell lymphoma." (PMID 36313435, 2022).
tauopathy (2 papers, 2016 to 2024). Neurodegenerative disorders involving deposition of abnormal tau protein isoforms (tau proteins) in neurons and glial cells in the brain. "In this work, we have illustrated the diversity and plasticity of microglial phenotypes and a conspicuous emergence of S100A8+ microglia in both accelerated aging and tauopathy." (PMID 38403918, 2024). "Importantly, S100A8‐positive microglia were also retrieved in brain biopsies of human AD and tauopathy patients as well as in a biopsy of an aged individual without reported pathology." (PMID 38403918, 2024). "Thus, the emergence of S100A8‐positive microglia portrays a conspicuous commonality between accelerated aging and tauopathy progression, which may have relevance for ensuing brain dysfunction." (PMID 38403918, 2024).
tonsillitis (2 papers, 2017 to 2021). Inflammation of the tonsillar tissue. "In addition, we will also examine the relevant pathways in order to explain the association of increased levels of IL-1ß, IL-18 and S100A8/A9 in patients suffering from recurrent tonsillitis." (PMID 34187480, 2021). "We will continue to examine the influence of S100A8/A9 on the pathomechanism of recurrent tonsillitis and its function in healthy tonsils." (PMID 34187480, 2021). "Elevated levels of IL-18, S100A8/A9 specifically in serum and IL-1β in saliva can be used as a novel, objective biomarkers and collectively scored using the RAT-score to identify patients with recurrent tonsillitis." (PMID 34187480, 2021). "Immunohistochemical findings revealed higher concentrations of S100A8/A9 in the tonsils of patients with PTA in contrast to hyperplastic tonsils without any history of tonsillitis." (PMID 29180834, 2017). "Staining for S100A8/A9 was strongly positive in tonsils of patients with PTA (3.30 ± 0.23 [mean score ± SD]) in contrast to hyperplastic tonsils without any history of tonsillitis (1.68 ± 0.22, p < 0.001)." (PMID 29180834, 2017).
urinary tract infection (2 papers, 2017 to 2020). "S100A8/A9USG had the highest sensitivity (96%) and specificity (66%) to detect TCC/PCA, with specificity reaching 75% after excluding dogs with a urinary tract infection." (PMID 28431528, 2017). "No impact of S100A8/A9 was also reported during urinary tract infection in S100A8/A9-/- mice." (PMID 32107497, 2020).
urticaria (2 papers, 2013 to 2025). A vascular reaction of the skin characterized by erythema and wheal formation due to localized increase of vascular permeability. "S100A7, S100A8, S100A9, S100A12, IL6 and SOCS3, whose mRNA expression correlated positively with the urticaria activity score and may have a potential diagnostic value." (PMID 40635160, 2025).
vaginitis (2 papers, 2014 to 2024). A non-infectious or infectious inflammatory process affecting the vagina. "However, more research is needed to address the role (if any) of inflammasome signaling during vaginitis and whether inflammasome activation may be linked to S100A8/9 production or PMN infiltration." (PMID 24699903, 2014). "Despite similar colonization among strains, those defective in hypha formation displayed significantly reduced immunological markers of vaginitis symptomatology (including reduced PMNs and S100A8)." (PMID 24699903, 2014). "Additionally, the study elucidated that BEPD regulates vaginitis and enhances vaginal barrier function in VVC mice by inhibiting the release of S100A8/A9 and downregulating the TLR4/MyD88/NF-κB signaling pathway." (PMID 38794163, 2024).
actinic keratosis (1 paper, 2021). A precancerous lesion of the skin composed of atypical keratinocytes. "Recent studies have shown that S100A8/A9 was highly expressed in cSCC than that in normal and actinic keratosis tissues, and in vitro experiments confirmed that the overexpression of S100A8/A9 could enhance the proliferation and invasiveness of cSCC." (PMID 34934042, 2021).
acute cholecystitis (1 paper, 2018). "Statistically, it seems that only the serum and urine levels of the S100A8/A9 biomarker can predict the need for surgery in acute cholecystitis." (PMID 30057651, 2018). "Moreover, the mean level of serum and urine S100A8/A9 in acute cholecystitis was significantly higher in the surgical group than in the nonsurgical group (P < 0.05)." (PMID 30057651, 2018). "In the diagnosis of “abdominal pain caused by acute cholecystitis,” the mean level of serum and urine of S100A8/A9, the WBC count, and serum amyloid A were higher than normal in the surgical group and only the WBC count and serum amyloid were higher than normal in the nonsurgical group." (PMID 30057651, 2018).
airway hyperresponsiveness (1 paper, 2025). "Studies have shown that serum S100A8/A9 levels correlate with lung function and airway hyperresponsiveness, suggesting that S100A8/A9 serves as a biomarker." (PMID 40723384, 2025).
alopecia (1 paper, 2025). Hair loss usually from the scalp. "S100A8 can promote ferroptosis through the NCF2/NOX2 pathway, thereby promoting cyclophosphamide-induced alopecia." (PMID 41035016, 2025).
alopecia areata (1 paper, 2021). Loss of scalp and body hair involving microscopically inflammatory patchy areas. "New drugs could act through modulation of the skin microbiota and/or stimulation of the innate immune response via AMPs such as S100a8/a9 and certain cytokines such as IL‐1β, thereby being potentially beneficial in conditions such as alopecia areata and other cutaneous diseases." (PMID 33629779, 2021).
Aortic dissection (1 paper, 2025). Aortic dissection refers to a tear in the intimal layer of the aorta causing a separation between the intima and the medial layers of the aorta. "Other novel inflammatory markers were also examined to determine their prognostic value in patients with Type A aortic dissection, such as S100A8/A9, pentraxin 3, chitinase 3-like 1, and S100B." (PMID 39910669, 2025).
artery occlusion (1 paper, 2025). "Previous studies have found that S100A8/A9 protein levels were elevated both systemically and at sites of coronary artery occlusion." (PMID 38062310, 2025).
Ascites (1 paper, 2023). Accumulation of fluid in the peritoneal cavity (between the layers of the peritoneum that lines the abdomen). "In univariate analysis, age, WBC count, creatinine, INR, ascites grade, platelet (PLT) count, TB, HE grade, BI, S100A8, and S100A9 were connected with 28/90-day mortality." (PMID 37469934, 2023).
bladder tumors (1 paper, 2012). "In bladder tumors, overexpression of S100A4, S100A8 or S100A11, but not S100A9 in cancer tissues is associated with stage progression, invasion, metastasis and poor survival." (PMID 22838504, 2012).
bladder urothelial cancer (1 paper, 2025). "The analysis revealed a significant positive association with multiple types of BC, such as stage IV and invasive BCs, suggesting that the S100A8 gene may be involved in the proliferation, invasion and migration of bladder urothelial cancer." (PMID 39895787, 2025).
brain edema (1 paper, 2020). Increased intracellular or extracellular fluid in brain tissue. "There was a reduction in the neurological scores of non-TBI animals with remarkable severe brain edema after the intracerebroventricular administration of S100A8." (PMID 33613176, 2020).
brain tumors (1 paper, 2025). "Protein S100-A8 exhibited a 4-fold reduction, whereas the Deleted in malignant brain tumors 1 protein decreased 3-fold." (PMID 40366920, 2025).
brucellosis (1 paper, 2024). Brucellosis is a bacterial infection that spreads from animals to people via unpasteurized dairy products or by exposure to contaminated animal products or infected animals. "Consistently, we also found that S100A8/A9 was markedly overexpressed in acute brucellosis patients." (PMID 39135683, 2024). "Interestingly, the cytokine detection data from plasma supports our scRNA‐seq analysis that acute brucellosis patients exhibit elevated levels of S100A8/A9 complex." (PMID 39135683, 2024). "The use of anti‐S100A8/A9 treatments in the acute brucellosis phase may modulate the production of these molecules and, in turn, attenuate the cytokine storm syndrome." (PMID 39135683, 2024). "Notably, brucellosis patients at the acute stage showed a significant increase in the expression of S100A8/A9 genes, providing further evidence for our hypothesis." (PMID 39135683, 2024). "Additionally, we also detected high expression of typical inflammatory cytokines (e.g., S100A8/9/12, IL1B, IL6, CXCL8, CCL2, CXCL10) in brucellosis patients during the acute phase." (PMID 39135683, 2024). "Therefore, blocking the binding of S100A8/A9 to TLR4 may inhibit the downstream pro‐inflammatory signal, making it a promising strategy for designing effective therapeutics against acute brucellosis." (PMID 39135683, 2024).
celiac disease (1 paper, 2023). An autoimmune genetic disorder with an unknown pattern of inheritance that primarily affects the digestive tract. "In addition, the expression of the gene encoding another member of s100 family—S100-A8—was downregulated in T84 cells after stimulation with anti-VP7 antibodies in order to evaluate mechanisms of the development of celiac disease." (PMID 37515094, 2023).
cervical squamous cell carcinoma (1 paper, 2014). A squamous cell carcinoma arising from the cervical epithelium. "Decreased expressions of S100A9 and S100A8 were observed in human cervical squamous cell carcinoma." (PMID 25298751, 2014).
cholera (1 paper, 2019). "Interestingly, the levels of S100A8 and WRS were higher in the lamina propria cells during the acute stage of cholera, suggesting that these two proteins might play an important role in the intestinal inflammatory response in the early-stage cholera." (PMID 31780718, 2019).
chronic allograft nephropathy (1 paper, 2015). "More importantly, determination of S100A8 transcripts in 28 allograft biopsies showed lower values in patients with acute rejection episodes who had graft loss through chronic allograft nephropathy compared to those with stable graft function." (PMID 25689147, 2015).
chronic cystitis (1 paper, 2015). Recurrent infections of the urinary bladder. "The increased expression of antimicrobial peptides such as RegIIIγ and the calgranulins (s100a8 and s100a9) is interesting because this increased expression is not sufficient to eliminate bacterial replication during chronic cystitis." (PMID 25569799, 2015).